AURKB (aurora kinase B)
Diseases named in the same sentence as AURKB in open-access papers (continued):
Sharing a sentence is not in itself a finding about the gene and the disease.
tumor (continued). "AURKB was overexpressed in LUAD tumor tissues (513 cases) when compared with 59 normal tissues (rank-sum test, p < 0.001)." (PMID 33612479, 2021). "The expression of AURKB in tumor samples was found to be higher than that of control samples with significant margins (p=0.072)." (PMID 33612479, 2021). "GSK1070916 exerts this effect by inhibiting AURKB/C and inhibits malignant cell proliferation in a wide range of tumour cell lines in vitro and in xenograft models of human tumours." (PMID 33725274, 2021). "Pharmacological inhibition of AURKB dramatically reduces nucleus size and tumor foci number surrounding the CL region in diethylnitrosamine-treated liver." (PMID 33510150, 2021). "In fact, 3 of the top 5 kinase genes include CDK1, PLK1, and AURKB, were significantly highly expressed in tumor tissues and significantly related to the overall survival of LUAD." (PMID 33123291, 2020). "At 22 days after tumor cell injection, the tumors with partial silenced AURKB were diminished compared with the scramble control tumors." (PMID 32863956, 2020). "AURKB is overexpressed in a wide range of tumor types and has been considered a marker of prognosis." (PMID 32761869, 2020). "S49076, a MET/AXL/FGFR inhibitor has been shown to negate AURKB activity and improve the anti-tumor efficacy of radiotherapy." (PMID 33202573, 2020). "In fact, 3 of top 5 kinase genes include CDK1, PLK1, and AURKB were significantly highly expressed in tumor tissues and significantly related to the overall survival of LUAD." (PMID 33178836, 2020). "Generally, the several researches have suggested the important role of AURKB in tumors and non-neoplastic disease." (PMID 31576249, 2019). "Our results indicate that AURKB is activated in NSCLC tumor cells with acquired resistance to EGFR TKIs and can be a therapeutic target in absence of resistance mutations." (PMID 31000705, 2019). "The fact that reduced expression levels of a mitotic gene lead to tumor appearance is a common issue for many other mitotic regulators such as AurKA, AurKB, PTTG1, and Mad2." (PMID 30862113, 2019). "To investigate the key role of AURKB, a gene encoding Aurora B, on BRCA, we searched the public databases to analyze the different levels of AURKB in normal and tumor tissues." (PMID 31244554, 2019). "Conversely, overexpression of FOXM1 (SCC-25 FOXM1 #2) in SCC-25 cells increased target gene transcripts involved in tumorigenesis (VEGFA and AURKB) and decreased those related to tumor suppression (TRAIL Receptor 1 and 2)." (PMID 30978209, 2019). "The radiomics feature that correlated the most with the tumor stage was the effective diameter, while the Aurora kinase B gene, AURKB (GE), represented the most useful genomic feature to predict the ER status." (PMID 30402486, 2018). "Correlative analysis revealed that, in men, CTAG2 expression was strongly correlated with known lactotroph tumor aggressiveness markers implicated in the cell cycle (CENPE, AURKB, CCNB1, ADAMTS6)." (PMID 30555413, 2018). "Among these, ERBB2, PTPRD, PTPRT, AURKB also correlated with node status, stage, tumor size and/or presence of metastasis." (PMID 29844865, 2018). "Even for the therapy-naïve study cohort, differential gene expression was a significant prognosticator within tumor sets defined by their WHO grades (WHO°I: AURKB, COX10, ECT2, UBE2C; WHO°II: LEPR, MN1; WHO°III: PTTG1, UBE2C)." (PMID 26894859, 2016). "In the case of AURKB, phosphorylation of CDCA8 by AURKB can play a role in promoting cell growth, survival and xenograft tumor growth." (PMID 26842935, 2016). "We found, for example, that even after strict false discovery rate (FDR) correction, EZH2 and AURKB levels showed robust positive correlation with triple negative (TN) malignancies and high Ki67 index, as expected from their role in tumor aggressiveness." (PMID 27863398, 2016). "Aurora kinase B was expressed in 259 (97.3%) of the tumor samples, in the range of 0-30% (Median 4%; interquartile range: 2–8.5%)." (PMID 25885472, 2015).
tumor (continued). "Fifteen-years disease-free and overall survival for patients with high percentage of Aurora kinase B positive tumor cells was 30% compared to 50% for patients with low percentage of Aurora kinase B positive tumor cells." (PMID 25885472, 2015). "A number of genes involved with this map are upregulated in this tumor, including the druggable target AURKB (log2ratio = 6.3)." (PMID 24204627, 2013). "Pharmacological inhibition of MOF or AURKB may effectively disrupt this oncogenic circuit, suppress tumor growth, and offer a novel avenue for intervention." (PMID 40710353, 2025). "The xenograft model in mice further verified the tumor-promoting effect of AURKB in vivo." (PMID 39927464, 2025). "We examined the mRNA expression levels of AURKB in tumor and normal tissues using information from TCGA and the GEO database to determine whether they are linked to HCC." (PMID 38396874, 2024). "Taken together, these findings strongly suggest that USP29 may promote the tumor formation and progression through stabilization of AURKB." (PMID 38233848, 2024). "AURKB overexpression often leads to cell multinucleation and polyploidy, which leads to tumorigenesis, and can affect the invasion, metastasis, and drug resistance of tumor cells." (PMID 38396874, 2024). "Additionally, it has been demonstrated that AURKB is crucial for tumor development, progression, and chemotherapy response." (PMID 39014265, 2024). "In sum, AURKB promoted CRC tumor growth through its activation of CCNE1 in vivo." (PMID 38713155, 2024). "Meanwhile, AURKB showed high expression in two different tumor status, tumor-free and with tumor." (PMID 38396874, 2024). "Hyperactivation of AURKB has been shown to result in aneuploidy and increased tumor formation." (PMID 39335162, 2024). "It was revealed that the growth of xenograft tumors developed from shAURKB-transfected cells was substantially inhibited compared with the control group; however, the introduction of CCNE1 overexpression readily abrogated the inhibition of AURKB knockdown on tumor growth." (PMID 38713155, 2024). "Similarly, the analysis results of paired samples of tumor and normal tissues from the TCGA database showed that the AURKB expression level was higher in tumors." (PMID 38396874, 2024). "Moreover, the expression of AURKB mRNA was also obviously elevated in hepatocellular carcinoma tissue compared with the healthy one, and it was found to be an independent marker of tumor aggressiveness and prognosis." (PMID 37318676, 2023). "The results showed that compared with the control group, the wound healing area of HCCC9810 cells was significantly reduced by AURKB knockdown, which inhibited the migration of tumor cells, while the overexpression of AURKB had the opposite effect and promoted the migration of RBE cells." (PMID 37318676, 2023). "AURKB is altered in several types of tumor cells, including HCC." (PMID 36992689, 2023). "As Aurora kinase B is a mitotic kinase that regulates chromosome segregation and cell cycle progression during mitosis, dual treatment with a SMO inhibitor and Aurora B/C kinase inhibitor might target both ciliated and mitotic tumor cells." (PMID 36394953, 2023). "Human Aurora kinase B has an important role in the cell cycle and is overexpressed in tumor cells." (PMID 36432091, 2022).
tumor (continued). "In addition, the interaction between LINC00324 and the neighboring gene AURKB is complex and tumor-specific." (PMID 36620587, 2022). "Hence, it has been shown that different genes such as P16, AURKA, and AURKB play an important role in tumor growth in ATC." (PMID 36482411, 2022). "Therefore, the present study was performed to explore the relationship between AURKB phosphorylation and resistance to PTX to expand the understanding of the roles of AURKB in tumor cells." (PMID 35088239, 2022). "A substantial number of studies have reported that AURKB is a tumor-related gene." (PMID 35088239, 2022). "A previous study described AURKB-related tumor-promoting and pro-survival effects in CRPC." (PMID 35853811, 2022). "Together with our data presented here, this suggests that in tumour cells, AURKB may act to maintain caspase-2 in a phosphorylated inactive state, thereby preventing apoptotic cell death that contributes to therapy resistance." (PMID 32811973, 2021). "However, both AURKA and AURKB expression were significantly inversely correlated with markers for T-cell infiltration of the tumor: CD3E, CD4, CD8A, LCK, PDCD1 and IFNG." (PMID 33123754, 2021). "Interestingly, in this research, two tumor suppressors (DLC1 and HLF) were both found to be closely correlated with AURKB and AURKB-associated differentially expressed miRNAs and hypermethylation." (PMID 33612479, 2021). "Although much progress has been made in elucidating the importance of AURKB in tumour biology, the involvement of AURKB in organ development remains largely unknown." (PMID 33462217, 2021). "Although much progress have been made in elucidating the importance of AURKB in tumor biology, the molecular mechanism of AURKB in gastric cancer progression, especially in modulating cell cycle progression and proliferation, remains largely unknown." (PMID 31982864, 2020). "Notably, silencing of AURKB profoundly reduced the sensitivity of tumor cells to HOl-07 that further attested the inhibitory activity of HOl-07 to AURKB." (PMID 33202573, 2020). "AURKB expression was examined in 8 pairs adjacent normal and ccRCC tumor tissues with western blot." (PMID 32194783, 2020). "Tumours were sorted according to the expression level of AURKA or AURKB mRNA." (PMID 32138169, 2020). "Tumor images are shown and knocking down AURKB significantly reduced both tumor volume and weight." (PMID 32863956, 2020). "The expression of AURKB tended to elevate with enhancing tumor T stage and G grade." (PMID 32194783, 2020). "Analyzing the expression and function of CDK1 and AURKB, the selected compounds could block cell proliferation and inhibit the growth of tumor." (PMID 32194417, 2020). "We compared AURKB mRNA expression between tumor tissues and normal tissues." (PMID 31576249, 2019). "Many studies have suggested that AURKB plays a vital role in tumorigenesis and tumor progression." (PMID 31576249, 2019). "Besides, a group recently demonstrated that daurinol, a novel topoisomerase inhibitor, can inhibit the transcriptional activity of both AURKA and AURKB, which increased the radio-sensitivity of tumor cells in vivo and in vitro." (PMID 28147341, 2017). "In order to determine the functional role of these kinases in KRAS-induced transformation, we generated KRAS-positive A549 and H358 cells with stable and inducible shRNA-mediated knockdown of AURKA or AURKB and evaluated transformation in vitro and tumor growth in vivo." (PMID 26842935, 2016). "Although we do not find over expression of Aurora kinase B in the fulvestrant resistant T47D cell lines, over expression of Aurora kinase B may be important for tumor cell growth." (PMID 25885472, 2015).
tumor (continued). "Inhibition of AURKB in tumor cells leads to growth inhibition and apoptosis." (PMID 19245677, 2009). "Thus, dual targeting of MOF and AURKB may provide a promising strategy to suppress tumor proliferation, potentially reducing chemotherapy dosage requirements and mitigating resistance." (PMID 40710353, 2025). "Our results reveal that reducing AURKB levels is the key to reversing the growth inhibition caused by BRCA2 deficiency–induced K-fiber instability and SAC activation, so how to reactivate the recognition of deficient K-fibers and ultimately kill BRCA2-deficient tumor cells is a very important issue." (PMID 37934606, 2024). "This indicates that expression changes of the TPX2/AURKB subnetwork likely reflect tumor intrinsic features while those of the COL1A2 subnetwork likely captures features of stromal cells in the tumor microenvironment impacted by alterations in tumor cell aurora kinase signaling." (PMID 35332150, 2022). "Moreover, the size of tumour xenografts decreased upon AURKB knockdown." (PMID 32429269, 2020). "Besides, AURKB also plays an important role in non-neoplastic disease." (PMID 31576249, 2019). "Given the central role of this regulatory axis in tumor progression, targeting MOF and AURKB represents a compelling therapeutic strategy." (PMID 40710353, 2025). "The highly expressed AURKB in RMS contributes to the apoptosis and ferroptosis resistance of tumor cells through the nucleophosmin 1 (NPM1)/Sp1 transcription factor (SP1)/acyl-CoA synthetase long-chain family member 5 (ACSL5) axis." (PMID 39927464, 2025). "When specificially examining the tumor samples alone, we found that the cycling HepT population expressed high levels of EZH2, SUZ12, and EED, along with cell cycle regulators MKI67, AURKB, ASPM, TOP2A, and HELLS." (PMID 40766612, 2025). "In the present study, the tumor-promoting role of AURKB in RMS was identified by genetic knockdown and using a highly selective AURKB inhibitor, AZD1152, and we found the regulatory effect of AURKB on ferroptosis in RMS." (PMID 39927464, 2025). "H3K18la epigenetically activates AURKB transcription, and elevated AURKB subsequently disrupts HNRNPM-mediated PSAT1 mRNA degradation, stabilizing PSAT1 expression and promoting tumor growth." (PMID 40784984, 2025). "IHC analysis of tumor tissues revealed reduced PSAT1 and Ki67 expression and elevated c-caspase 3 levels following AURKB knockdown." (PMID 40784984, 2025). "AURKB, a critical node downstream of the FTO/SP1/AURKB pathway, can modulate the tumor microenvironment of GC and drive its malignant progression." (PMID 41312360, 2025). "EZH2, AURKB, GPC3, CTNNB1, and TGFβ were significantly upregulated in tumor tissues, indicating their potential roles in tumor progression." (PMID 40766612, 2025). "These include the overexpression of PLK1, AURKB, BIRC5 (survivin, 1.23 log2FC), and certain CENP isoforms, suggesting that HS tumor cells undergo unrestrained mitosis." (PMID 40149290, 2025). "Among them, PHF19, AURKA, CHAF1B and AURKB were up-regulated in the tumor group, NAP1L2, TONSL, SATB2 and HDAC9 were down-regulated in the tumor group." (PMID 38212708, 2024). "The analysis of showed that PHF19, AURKA, CHAF1B and AURKB were up-regulated in the tumor group, NAP1L2, TONSL, SATB2 and HDAC9 were down-regulated in the tumor group." (PMID 38212708, 2024). "To further explore the function of AURKB and MAD2L2 in vivo, we established a T24 xenograft tumor model in nude mice." (PMID 38515112, 2024). "These genes formed a highly interconnected network, with key central nodes such as AURKB, CEP55, CCNB2, and MCM10, suggesting their involvement in common pathways potentially driving aggressive tumor behavior and contributing to poor patient prognosis." (PMID 39596419, 2024).
tumor (continued). "They identified AQP5, KiSS-1, FZD7, AURKB, UBE2C, and PTTG1 as overexpressed in recurrent CNs, suggesting these genes play a role in tumor progression." (PMID 39066950, 2024). "Correlation analysis revealed a significant correlation of AURKA, AURKB, BUB1, HJURP, TOP2A, and TTK with tumor proliferation, G2M checkpoint, MYC targets, and DNA replication." (PMID 38726001, 2024). "The protein expression of AURKB and CCNE1 in tumor tissues from the three treatment groups were confirmed using western blot." (PMID 38713155, 2024). "We have demonstrated that an AURKB/CASP-2 mechanism, regulated by the levels of BID, determines the fate of tumor cells after abrogation of the spindle assembly checkpoint by AURKB or TTK inhibitors." (PMID 37443114, 2023). "To determine the preclinical efficacy of AURKB inhibition in suppressing the emergence of cisplatin-tolerant persister HNSCC cells, we used an in vivo mouse tumor xenograft model and treated it with a combination of cisplatin and barasertib." (PMID 36982384, 2023). "Expression of these genes was validated using immunohistochemistry or immunofluorescence staining in both PDCs and respective tumor tissue, and this was recapitulated on flow cytometry for AXL (HN137) and AURKB (HN159 and HN220)." (PMID 36973261, 2023). "In this tumor type, CDK6 and FGFR2 were less expressed than in normal tissue, whereas CDK7, MET, ALK and AURKB stood out as upregulated in tumor samples." (PMID 36839989, 2023). "After 6 weeks, tumor volume lessened in the HCCC9810 cell group with AURKB knockdown and increased in mice inoculated with AURKB overexpressed RBE cells." (PMID 37318676, 2023). "As expected, AURKB, CCNA2, and PLK1 were upregulated in the tumor cell line compared to that in normal gastric epithelial cells." (PMID 37238607, 2023). "Six of them (KIF4A, ASPM, KIF20A, KIF14, TPX2, KIF18B) are overexpressed by more than 10-fold in tumor samples and four of them (KIF11, AURKB, TPX2 and KIFC1) are essential for cell survival." (PMID 37835564, 2023). "Among the kinases that play a key role in promoting tumor proliferation, controlling mitosis progression, there are serine/threonine Aurora kinases, which include Aurora A (AURKA), Aurora B (AURKB) and Aurora C (AURKC)." (PMID 35884618, 2022). "Cell cycle-related genes such as AURKA, AURKB, GTSE1, CCNA2, and MYBL2 were shown to promote tumor progression of LUAD." (PMID 36304306, 2022). "The expression of AURKB was found to be higher in HCC than in a control and was consistently correlated with patient tumor stage." (PMID 36557005, 2022). "AURKA and AURKB play key roles in mitosis, and some natual products targeting AURKA and AURKB exert anti-tumor effects in vitro." (PMID 35699421, 2022). "We then examined the expression of 9 model genes in single cells and found that CDK1, AURKB, CCNA2, and CHEK1 are mainly expressed in CD4 cells, while PRKAA2, CDK5, and PRKCD are mainly expressed in tumor cells." (PMID 36120466, 2022). "CDK1, AURKB, CCNA2, and CHEK1 were highly expressed in immune cells, suggesting that histone phosphorylation is closely related to the tumor immune environment." (PMID 36120466, 2022). "These include three members of the Aurora kinase family (AURKA, AURKB, and AURKC), serin/thereonine kinases that regulate multiple aspects of tumor growth and progression." (PMID 36482411, 2022). "Human ovarian cortex tissue with experimentally induced tumour foci of CML, AML and primary cells of AML patients were exposed to a 24h treatment with 1 μM GSK1070916, an AURKB/C inhibitor, to eliminate malignant cells by invoking mitotic catastrophe." (PMID 33725274, 2021). "To evaluate the potential of AURKB as a prognostic marker in blood samples, we obtained the data of 80 LUAD tumor samples and 80 normal control samples from the GEO database (GSE20189)." (PMID 33612479, 2021).